LINC01415 (long independently transcribed non-coding RNA 1415)
Synonyms: TCONS_00026208
Gene: Long non-coding RNA gene on chromosome 18 (55,776,727 to 55,781,722, reverse strand). Ensembl gene ENSG00000267325.
Diseases named in the same sentence as LINC01415 in open-access papers:
LINC01415 is named in the same sentence as 4 diseases in open-access papers, as found by Europe PMC text mining. Sharing a sentence is not in itself a finding about the gene and the disease. The quoted sentences say what the papers report.
esophageal cancer (1 paper, 2018). A primary or metastatic malignant neoplasm involving the esophagus. "Further somatic copy number variation analyses revealed that lncRNAs genome loci copy number amplifications or deletions are involved in part of lncRNAs dysregulation in esophageal cancer tissues, such as PVT1, LINC00887, LINC00964, LINC01415, and WEE2‐AS1." (PMID 29926523, 2018).
lung adenocarcinoma (1 paper, 2022). A carcinoma that arises from the lung and is characterized by the presence of malignant glandular epithelial cells. "Compared with normal lung-epithelial cells (BEAS-2B), the expression level of LINC01415, FRMD6-AS1 and FAM83A-AS1 was significantly higher in lung adenocarcinoma cells (A549/PC9), while the expression level of MED4-AS1 and LINC01480 was lower in lung adenocarcinoma cells." (PMID 36186456, 2022).
cancer (1 paper, 2024). A tumor composed of atypical neoplastic, often pleomorphic cells that invade other tissues. "The more cancer-specific lincRNAs are LINC00470, LINC00668, LINC00907, LINC01254, LINC01415, LINC01478, and LINC01539." (PMID 38540157, 2024).
tumor (1 paper, 2020). "High expression of SPP1, BGN, LINC01614, and LINC01415 in tumor samples was validated further by RT-qPCR." (PMID 33362844, 2020). "Expression of BGN, SPP1, LINC01415, and LINC01614 was much higher in tumor samples than in normal esophageal tissues." (PMID 33362844, 2020).